APOL1 (apolipoprotein L1)
Diseases named in the same sentence as APOL1 in open-access papers (continued):
Sharing a sentence is not in itself a finding about the gene and the disease.
chronic kidney disease (continued). "Current therapies for chronic kidney disease are less effective at preventing progressive loss of kidney function in individuals with APOL1 high risk genotype, compared to other forms of glomerular disease, even when there may be a reduction in proteinuria in a particular patient." (PMID 34765626, 2021). "We then assessed alleles affecting APOL1 function which are associated with chronic kidney disease (CKD) in African Americans." (PMID 34261517, 2021). "In the USA, the higher prevalence of chronic kidney disease and progression to end-stage kidney disease in African Americans than in other population groups might partly be attributable to the presence of chronic kidney disease risk variants of apolipoprotein L1 (APOL1)." (PMID 31708144, 2019). "Moreover, clinical utility of APOL1 testing for chronic kidney disease risk in African ancestry patients may differ from using genetic testing to diagnosis monogenic diabetes and, as such, may limit the interpretation of the results of this study." (PMID 30042363, 2018). "While they confer protection against the parasite Trypanosoma brucei, genetic variants in the APOL1 region of chromosome 22 have been identified as major determinants of chronic kidney disease (CKD) in African Americans." (PMID 25884165, 2015). "For the kidneys, IFN-γ, in concert with APOL1 gene expression, can induce pyroptotic angiopathy in renal endothelial cells, accelerating the progression of chronic kidney disease (CKD)." (PMID 40661082, 2025). "The Janus kinase-STAT Inhibition to Reduce APOL1-Associated Kidney Disease (JUSTICE) trial is evaluating the antiproteinuric efficacy and safety of baricitinib in patients with APOL1-associated FSGS and HTN-attributed chronic kidney disease (HTN-CKD)." (PMID 39291185, 2024). "Clear examples such as African-enriched variants in APOL1 and G6PD have been shown to contribute to especially high risk of chronic kidney disease and to missed diabetes diagnosis, respectively." (PMID 36873096, 2023). "Individuals of African ancestry present an increased risk of chronic kidney disease (CKD) and kidney failure in the context of the presence of a polymorphism in the APOL1 gene." (PMID 37685436, 2023). "Around 87% of PLWHIV with chronic kidney disease (CKD) in Nigeria had two APOL1 risk alleles." (PMID 37872903, 2023). "Patients from two large cohorts, the African American Study of Kidney Disease and Hypertension (AASK) study, and the Chronic Renal Insufficiency Cohort (CRIC) study, were stratified by number of copies of high-risk APOL1 variants." (PMID 36578658, 2022). "According to the candidate gene approach, two gene defects have been associated with kidney chronic disease which are the myosin heavy polypeptide 9 (MYH9) and APOL1 polymorphisms in populations of African ancestry." (PMID 36672600, 2022). "Variants of the apolipoprotein L1 (APOL1) gene, G1 and G2 make African-Americans prone to lupus nephritis-associated end-stage renal disease." (PMID 35186921, 2022). "Like PE, chronic kidney disease (CKD) also is more prevalent in African Americans, and the recent description of two polymorphisms in the APOL1 gene has advanced our understanding of the increased risk for CKD in African Americans." (PMID 32434471, 2020). "Three coding variants in the apolipoprotein L1 (APOL1) gene are significantly associated with susceptibility to FSGS and a spectrum of chronic kidney disease (CKD) in African Americans15,16." (PMID 31754646, 2019). "An elegant example of this is variants of the apolipoprotein L1 gene (APOL1), which, while reducing the risk of trypanosomiasis, increase the risk of hypertension-associated chronic kidney disease." (PMID 28992220, 2018). "Information about APOL1 genetic variants, APOL1G1 and APOL1G2, is provided along with the association of these variants with hypertension-attributed end-stage renal disease (ESRD) and focal segmental glomerulosclerosis (FSGS)." (PMID 28842513, 2017).
chronic kidney disease (continued). "Reduced APOL1 and nephrin levels were also found in biopsies of patients suffering from end stage renal diseases." (PMID 27138898, 2016). "Meanwhile, the understanding of APOL1 genetic risk variants in conferring susceptibility to common kidney diseases, including FSGS, chronic kidney disease, and hypertension, is evolving." (PMID 26156092, 2015). "Recently, apolipoprotein L1 (APOL1) has been reported to be associated with FSGS lesions, a progressive course in HIV-related nephropathy, and chronic kidney disease." (PMID 24308295, 2013). "The characterization of the associations between chronic kidney diseases (CKD) and polymorphisms on chromosome 22q12, namely MYH9 and APOL1 was an immense breakthrough for population-based genetic studies of CKD." (PMID 23285077, 2012). "Individuals of African ancestry carrying APOL1 (apolipoprotein L1) high-risk genotypes face a markedly increased risk of kidney failure, yet tools to identify those individuals likely to progress to chronic kidney disease are lacking." (PMID 41986737, 2026). "The most common carrier genes detected were not KSD-associated, including susceptibility to end stage renal disease (APOL1, N = 16), congenital nephrotic syndrome type 2 (NPHS2, N = 6), sickle cell disease (HBB, N = 3), and methylmalonic aciduria (MUT, N = 3)." (PMID 40126616, 2025). "Relationships between G1 and G2 APOL1 variants and several non-communicable diseases including chronic kidney disease are well-established in African American populations." (PMID 38360481, 2024). "Chronic kidney disease is more common in individuals of African descent in the U.S. Prior studies support African-derived SNVs at another gene (APOL1), related to resistance to infectious diseases in Africa, conferring risk to chronic kidney disease in Hispanics/Latinos with West African admixture." (PMID 37461045, 2023). "In a study performed on an El Salvadoran population affected by end-stage renal disease, neither APOL1 genotype frequencies nor risk haplotype frequencies were found to be significantly associated with HbAS." (PMID 37240547, 2023). "APOL1 high risk genotype (HRG), defined as two variants in any combination (G1/G1, G1/G2, or G2/G2), has been associated with several adverse phenotypes including chronic kidney disease and microvascular stroke; however, these associations are highly variable." (PMID 36238153, 2022). "In people of African heritage, G1 and G2 coding variants of the APOL1 gene are associated with non-diabetic end stage renal disease (ESRD) and contribute to nearly 70% of cases." (PMID 35207681, 2022). "In addition, genetic variations in two coding regions of Apolipoprotein L1 (APOL1) and Heme oxygenase 1 (HMOX1) genes have been associated to chronic kidney disease, and to SCD nephropathy." (PMID 33790942, 2021). "Chronic kidney disease (CKD) is a large public health burden that disproportionately impacts African Americans and other individuals of recent sub-Saharan African ancestry, in part owing to coding variants in the APOL1 gene." (PMID 34350953, 2021). "The strong association between APOL1 gene expression with several non-diabetic chronic kidney diseases and its mechanisms have been extensively investigated using animal or cell models created by gene editing." (PMID 34440683, 2021). "Variations in apolipoprotein L1, encoded by the APOL1 gene, are predisposing factors for focal segmental glomerulosclerosis, chronic renal and end-stage renal disease in African Americans, which may be related to renal blood flow impairment." (PMID 34300206, 2021). "The mechanism of pathogenesis associated with APOL1 polymorphisms and risk for non-diabetic chronic kidney disease (CKD) is not fully understood." (PMID 34138902, 2021). "For example, the presence of susceptibility variants in particular gene loci (e.g., the loci of UMOD and APOL1), may increase the risk of CKD and increase the possibility of end stage renal disease (ESRD) in specific populations." (PMID 32224869, 2020).
chronic kidney disease (continued). "APOL1 also interacts with VAMP8-coated vesicles, inducing a reduction in local dynamics of the C-terminal which in turn causes progressive and repeated injury, leading to chronic kidney disease in susceptible African Americans subjects." (PMID 31929905, 2019). "We examined the prevalence of APOL1 genotypes and associated cardiovascular phenotypes among children with FSGS in the Chronic Kidney Disease in Children (CKiD) study; an ongoing multicenter prospective cohort study of children aged 1–16 years with mild to moderate kidney disease." (PMID 27900314, 2016). "The myosin, heavy-chain 9, non-muscle (MYH9) and apolipoprotein L1 (APOL1) genes have been associated with risk for focal segmental glomerulosclerosis and end-stage renal disease in African Americans." (PMID 25962948, 2015). "In this study, we report the findings from a case/control association analysis of non-diabetic chronic kidney disease and variants in APOL1 and MYH9 genes in an African sample from southwest Nigeria." (PMID 22956460, 2013). "Single nucleotide polymorphisms (SNPs) in MYH9 and APOL1 on chromosome 22 (c22) are powerfully associated with non-diabetic end-stage renal disease (ESRD) in African Americans (AAs)." (PMID 21698141, 2011). "The GSE81492 dataset consists of 10 kidney samples of APOL1 mutant mice, which is a mouse model of chronic kidney disease (CKD)." (PMID 38689377, 2024). "Apolipoprotein L1 is encoded by the APOL1 gene, which carries well-established risk variants associated with a wide spectrum of kidney-related diseases, including focal segmental glomerulosclerosis (FSGS), HIV-associated nephropathy (HIVAN) and hypertension-associated end-stage renal disease (ESRD)." (PMID 37969018, 2023). "APOL1 high risk variants are present at high frequencies in populations of West African descent and account for much of increased risk of non-diabetic chronic kidney disease." (PMID 36580463, 2022). "However, direct experimental evidence of the physiologic role of APOL1 in podocytes and of the pathogenic mechanisms of the APOL1 variants in the development of chronic kidney disease is still lacking and animal models have not been described so far." (PMID 27138898, 2016). "The frequencies of apolipoprotein L1 (APOL1) variants and their associations with chronic kidney disease (CKD) vary substantially in populations from Africa." (PMID 26112018, 2015). "Using admixture mapping, APOL1 has been identified as a risk gene for non-diabetic end-stage renal disease in African Americans; whether this gene is also associated with eGFR is unknown." (PMID 23028791, 2012). "Proteins with high disease scores (76–100% confidence) for both hypertension and chronic kidney disease included angiotensinogen (AGT), albumin (ALB), apolipoprotein L1 (APOL1), and uromodulin (UMOD)." (PMID 38402394, 2024). "Finally, we tested whether any of the APOL1 genotypes were associated with an excess of ICD-9 and ICD-10 codes using logistic regression with age, sex, Townsend deprivation index, evidence of chronic kidney disease, and principal components 1–4 used as covariates." (PMID 38360481, 2024). "Despite the long-term sequelae of preeclampsia, which includes increased risk of hypertension, cardiovascular disease, chronic kidney disease (CKD) and end stage renal disease (ESRD) among women of African descent, little is known about genetic risk factors such as apolipoprotein L1 (APOL1) risk." (PMID 36580463, 2022). "A variant in the apolipoprotein L1 (APOL1) gene that is associated with non-diabetic chronic kidney disease (CKD) in patients of African American ancestry is being returned in a pilot study at the Mount Sinai Medical Center." (PMID 24723935, 2014). "After collection of urine samples from the six participants carrying APOL1 HRG, only cells harvested from one G2/G2 carrier who had stage 3 chronic kidney disease and proteinuria proliferated successfully and twelve conditionally immortalised clones were generated." (PMID 34440683, 2021).
chronic kidney disease (continued). "The spectrum of APOL1-associated kidney disease is quite diverse and includes nephrotic syndrome (FSGS), non-diabetic chronic kidney disease secondary to hypertension, HIV-associated collapsing glomerulopathy, sickle cell nephropathy, and lupus nephritis." (PMID 27148508, 2016). "Genetic variants in MYH9 are associated with non-diabetic chronic kidney disease, FSGS and HIV nephropathy, however whether the association is due to a functional variant in MYH9 or due to LD with nearby Apolipoprotein L1 (APOL1) remains a point of controversy." (PMID 29665793, 2018). "Although recent studies have provided statistical evidence implicating APOL1 variation in nondiabetic nephropathies, MYH9 risk variants are still associated with chronic kidney disease (CKD) in non-African American populations and in sickle cell disease nephropathy." (PMID 26147622, 2015).
Nephropathy (96 papers, 2011 to 2026). A nonspecific term referring to disease or damage of the kidneys. "Given the high similarity between Drosophila nephrocytes and human podocytes, our findings suggest ER stress as a new therapeutic target for HIV-1- and APOL1-associated nephropathies." (PMID 40747773, 2025). "This gain-of-function mutation in APOL1 triggers podocyte toxicity through endoplasmic reticulum stress, autophagy, and disruptions in ion flow, leading to the development of associated nephropathies such as FSGS." (PMID 40948471, 2025). "These variants impair APOL1 function, causing podocyte injury, proteinuria, and progressive kidney damage." (PMID 40213244, 2025). "Among these, Apolipoprotein L1 (APOL1) has emerged as a gene of particular interest due to its central role in APOL1-associated nephropathies, a group of disorders where FSGS represents a prominent clinical manifestation." (PMID 40948471, 2025). "The Drosophila nephrocyte has been well established to study the pathogenesis of APOL1-associated nephropathies." (PMID 40747773, 2025). "Extensive research has demonstrated that two specific risk variants of APOL1 (G1 and G2) significantly contribute to kidney disease progression, particularly within the context of APOL1-associated nephropathies." (PMID 40948471, 2025). "Hereby we present a case of CG in a SLE patient with homozygous APOL1 high-risk variant for nephropathy and diagnosis of acute parvovirus infection." (PMID 39792859, 2025). "The present case is unique because it presented two possible etiologies that justify clinical and histologic findings along with a nephropathy high-risk APOL1 genotype." (PMID 39792859, 2025). "Interaction of this motif with the podocyte plasma membrane is involved in cytotoxicity associated with APOL1 variant nephropathy, and this cytotoxicity is lost upon N264K mutation, which is expected to prevent cholesterol interaction." (PMID 40503184, 2025). "This probably explains why the prominent pathology resulting from interference with APOL1 and APOL3 functions, as occurs following the expression of the APOL1 C-terminal variants G1 or G2, is nephropathy." (PMID 39768205, 2024). "APOL1 genetic risk alleles (G1/G2) have been identified as susceptibility factors for the development of several nephropathies including HIV-associated nephropathy and shown to contribute to podocyte injury." (PMID 38891023, 2024). "Our organoid model supports the blockade of IFN signaling as a potential therapeutic strategy to mitigate the risk of APOL1-mediated nephropathy." (PMID 38838223, 2024). "The link between APOL1 renal risk alleles and miR193a needs to be studied further in vivo to understand the role of miR193a in causing or perpetuating APOL1 nephropathy." (PMID 36830635, 2023). "APOL1-RA associated nephropathies include focal segmental glomerulosclerosis (FSGS), HIV-associated nephropathy (HIVAN), hypertension-associated end stage kidney disease (ESKD), sickle cell nephropathy, and lupus nephritis." (PMID 37925499, 2023). "Of particular interest is the reduced APOL1-mediated cell death after pharmacological inhibition, suggesting ER stress as a central pathway in the pathogenesis of APOL1-associated nephropathies." (PMID 37171583, 2023). "The APOL1 G1 and G2 variants protect from trypanosomiasis but predispose to the development of non diabetic kidney diseases often referred to as APOL1 associated nephropathy." (PMID 36034035, 2022). "APOL1 is an example of how knowledge of ancestry-specific alleles can have clinical utility for Mendelian nephropathies and for more widespread, complex forms of CKD." (PMID 35207681, 2022). "The apolipoprotein L1 (APOL1) gene (APOL1) variants such as its G1 and G2 alleles are associated with increased risk for nephropathy progression in African Americans including FSGS and human immunodeficiency virus-associated nephropathy (HIVAN)." (PMID 35223901, 2022).